VEGFA (vascular endothelial growth factor A)
Diseases named in the same sentence as VEGFA in open-access papers (continued):
Sharing a sentence is not in itself a finding about the gene and the disease.
glioma (continued). "Recent studies have examined the associations of specific SNPs in the VEGFA gene with glioma risk, but the significance of these findings remains unclear." (PMID 29137376, 2017). "In conclusion, the statistical data presented in this study suggest that variants of the VEGFA gene might be important in promoting the development of glioma in Chinese." (PMID 29137376, 2017). "Finally, although subgroup analysis was performed based on genotyping method and HWE in controls, we did not design further analyses to investigate associations between VEGFA SNPs and glioma subtype because of limited data." (PMID 29137376, 2017). "The minor allele of VEGFA rs3025039 was related to a significantly increased glioma risk under the allele contrast (OR = 1.209, 95% CI = 1.088–1.343, P < 0.001), recessive (OR = 1.973, 95% CI = 1.489–2.615, P < 0.001), and homozygous models (OR = 1.982, 95% CI = 1.491–2.635, P < 0.001)." (PMID 29137376, 2017). "Finally, we examined whether CD31, EGFR, and VEGFA expression were associated with glioma’s prognosis in the TCGA dataset." (PMID 37534312, 2023). "Our results indicated that several VEGFA polymorphisms might be risk factors for glioma in Chinese." (PMID 29137376, 2017). "Although our previous study demonstrated that LRIG3 inhibited angiogenesis via the PI3K/AKT/VEGFA pathway under normoxia, its impact on glioma vascularization under hypoxia remains elusive." (PMID 41692232, 2026). "Other notable signals included IL6, VEGFA, TGFB1, and ANXA1, genes associated with mesenchymal transition, angiogenic niches, and poor prognosis in glioma." (PMID 41514565, 2025). "Bevacizumab has already been used in the treatment of certain glioma patients, targeting VEGFA to inhibit blood vessel formation and tumor growth." (PMID 40881678, 2025). "The PPI showed that VEGFA and XBP1 are key genes linked to HIF-1α and that co-expression affected glioma prognosis." (PMID 40621799, 2025). "Studies have shown that VEGFA plays a critical role in promoting angiogenesis, stemness maintenance, and immune evasion in glioma." (PMID 40881678, 2025). "Xenografted tumour cells of a glioma have also previously been shown to induce the ectopic production of zebrafish pro-angiogenic growth factors including VEGFA and its receptor VEGFR2, accompanied by increased SIV branching." (PMID 40469193, 2025). "In the glioma microenvironment, macrophages secrete VEGFA, stimulating angiogenesis and supporting glioma growth." (PMID 39479394, 2024). "We found that in glioma cells, IDO1 overexpression only activated the GCN2 pathway and upregulated VEGFA expression if it caused a drastic decrease in Trp levels." (PMID 39065567, 2024). "The release of VEGFA and semaphorin 3A (Sema 3A) by tumor cells, including glioma, further activates NRP1, triggering the activation of VEGFR1 and subsequent recruitment of TAMs in glioma." (PMID 39033204, 2024). "MDIG is an oxygen-sensitive protein that promotes angiogenesis and glioma growth by activating the EGFR/p-EGFR/VEGFA/VEGFR1/R2 pathway." (PMID 38687357, 2024). "Bevacizumab and aflibercept can cause a decrease in VEGFA effects and an increase in CD206 + and Tie-2 + macrophages in murine and human gliomas through increasing Ang2 levels." (PMID 39003350, 2024). "The novel lncRNA INC01116, when knocked down, suppresses growth, invasion, metastasis, tumorigenesis, and angiogenesis in glioma both in vitro and in vivo by regulating VEGFA expression." (PMID 39682093, 2024). "Circ-ATXN1 served as a miR-526b-3p sponge to inhibit the function of miR-526b-3p to downregulate MMP2/VEGFA expression, leading to glioma angiogenesis." (PMID 38075205, 2024). "Circ-RPL15 stimulated proliferation and migration of gliomas by sponging miR-146b-3p and then upregulating VEGFA." (PMID 38075205, 2024). "The interaction between miR-34a-5p and VEGFA has been documented in hepatocellular carcinoma, glioma, and endometriosis." (PMID 37573538, 2024).
glioma (continued). "In a nutshell, lncRNA SNHG15 promoted the growth of glioma microvascular endothelial cells primarily by positively regulating the miR-451/VEGFA/Cdc42 axis, thereby pointing to possible diagnostics and therapeutics based on the axis." (PMID 37056344, 2023). "In particular, in U87-MG cells, Survivin, VEGFA, and c-Myc levels were 62%, 44%, and 39%, which were lower than those in normal glioma cells." (PMID 37057281, 2023). "Further, we confirmed that SPRY4‐IT1 regulated the miR‐101‐3p/EZH2/VEGFA signaling axis to induce tumorigenesis and angiogenesis in glioma." (PMID 36479622, 2023). "The overexpression of miR-205 inhibits glioma cells’ invasive behavior and improves apoptosis and cell-cycle arrest at the G1/G0 phase by targeting vascular endothelial growth factor A (VEGF A), which is the most potent mediator of angiogenesis in glioma." (PMID 37509289, 2023). "POSTN was reported to enhance the resistance of glioma stem cells to anti-angiogenic therapy by positively regulating VEGFA expression through activation of STAT3." (PMID 37461041, 2023). "We carried out immunohistochemical staining of the CD31, EGFR, and VEGFA proteins in primary glioma of tumor sites and hyperperfusion sites." (PMID 37534312, 2023). "Our results indicate that miRNA-383-5p functions as an anti-oncogene by inhibiting the VEGFA/Akt/mTOR signaling pathway in glioma cells." (PMID 37592783, 2023). "miRNA-383-5p and VEGFA/Akt/mTOR pathway play important regulatory roles in the malignant biological behavior of glioma." (PMID 37592783, 2023). "Mechanistically, SNHG15 elevated VEGFA and Cdc42 expression by sponging miR-451 at the post‐transcriptional level, facilitating the angiogenesis of glioma." (PMID 37056344, 2023). "In this work, we have reported miRNA-383-5p to act as a glioma suppressor and found it to inhibit aggressive glioma cell biological behavior via downstream regulation of VEGFA/mTOR." (PMID 37592783, 2023). "Mechanistically, SPRY4‐IT1 upregulated EZH2 expression by sponging miR‐101‐3p to induce VEGFA expression in glioma cells." (PMID 36479622, 2023). "By analyzing the transcriptional profiling of glioma from CCGA 22–24, it revealed that higher expression of VEGFA was also associated with poor prognosis for recurrent lower grade astrocytoma (log-rank test, P = 0.009)." (PMID 37741941, 2023). "Tumor tissue taken in these areas was rich in CD31, VEGFA and EGFR that were associated with poor prognosis in glioma patients." (PMID 37534312, 2023). "HOXC10 overexpression has been reported to facilitate the proliferation, migration, and angiogenesis of HUVECs, and is revealed to induce angiogenesis in gliomas by upregulating vascular endothelial growth factor A (VEGFA)." (PMID 37876483, 2023). "In our study, we found that the expression of VEGFA was stably downregulated in SPRY4‐IT1‐silenced glioma cells, while VEGFA was strongly upregulated in SPRY4‐IT1‐overexpressed cells." (PMID 36479622, 2023). "The tumorigenesis of glioma is regulated by the miRNA-383-5p direct target VEGFA and the downstream mTOR signaling pathway, which highlights the value of researching VEGFA as a therapeutic target for glioma." (PMID 37592783, 2023). "Our findings provide compelling evidence showing that SPRY4‐IT1 upregulated EZH2 to induce VEGFA by sponging miR‐101‐3p, thereby achieving cell proliferation and angiogenesis in glioma." (PMID 36479622, 2023). "Collectively, these results suggest that miRNA-383-5p inhibits apoptosis in glioma cells by inhibiting the expression of VEGFA." (PMID 37592783, 2023). "One of the most pivotal pro-angiogenic growth factors involved in glioma angiogenesis is vascular endothelial growth factor A (VEGF-A)." (PMID 37240099, 2023). "MiR-34a-5p downregulation promoted glioma cell growth, invasion and migration but VEGFA knockdown reversed the effect of miR-34a-5p downregulation on tumorigenesis." (PMID 37234708, 2023).
glioma (continued). "RNA‐sequencing and western blotting confirmed that SPRY4‐IT1 regulated EZH2 and VEGFA expression in glioma cells." (PMID 36479622, 2023). "Consistently, the VEGFA concentration in the conditioned medium from SPRY4‐IT1‐silenced or SPRY4‐IT1‐overexpressed glioma cells was decreased and increased, respectively." (PMID 36479622, 2023). "In this study, we identified the high expression of VEGFA in necrosis regions of high-grade gliomas." (PMID 37741941, 2023). "The findings of this study indicated that radiation-induced HBMVEC-derived GDF15 promoted VEGFA production in U373 glioma cells and consequently enhanced angiogenesis in glioma." (PMID 35280749, 2022). "We observed increased tumor cell apoptosis and decreased expression and secretion of vascular endothelial growth factor A in LPPR5OE glioma." (PMID 35328529, 2022). "For instance, circITGA7 accelerates glioma progression via miR-34a-5p/VEGFA axis; circSEPT9 promotes the malignant behaviors in glioma cells via miR-432-5p-mediated regulation of LASP1." (PMID 35059468, 2022). "Paired box 6 (PAX6) is a DNA-binding transcription factor that downregulates the expression of the vascular endothelial growth factor A (VEGFA) gene in glioma cells to suppress tumor cell invasion." (PMID 35935861, 2022). "ISL2 stimulates the expression of VEGFA at transcriptional level in glioma stem cells (GSCs), inducing the angiogenesis via ERK signaling." (PMID 35090496, 2022). "GDF15 promotes tumor angiogenesis through a positive feedback loop comprising EC-secreted GDF15, glioma-derived VEGFA, and KDR on ECs." (PMID 35280749, 2022). "It has been reported that angiogenic activity of LncRNA SNHG15 is regulated by suppressing miR-153, which targets VEGFA and cdc42 in glioma." (PMID 36158686, 2022). "Other studies found that RP11-732M18.3 was highly overexpressed in glioma cells, which not only promote glioma angiogenesis by accelerating the transcription and secretion of VEGFA but also facilitate glioma growth through accelerating p21 degradation." (PMID 36311792, 2022). "In summary, this study demonstrated that IR directly promotes the secretion of GDF15 from brain ECs and that GDF15 activates the VEGFA promoter in glioma cells through the p-MAPK1/SP1 pathway and consequently enhances angiogenesis in orthotopic brain tumors." (PMID 35280749, 2022). "Glioma stem cells were discovered to release vascular endothelial growth factor A and to form tubule-like structures in vitro when they were enclosed within the scaffold." (PMID 36582589, 2022). "Our data indicated that VEGFA level was increased in glioma tissues and played a carcinogenesis role." (PMID 33962397, 2021). "To further detecting B7H3 and VEGFA expression levels in human glioma specimens, we randomly picked out 9 of 2-HGhigh, 8 of 2-HGlow, and 4 IDH1-WT glioma samples to conduct IHC staining for B7H3 and VEGFA." (PMID 34079802, 2021). "Studies have shown that VEGFA is upregulated in glioma 9 and is essential for the development of the disease." (PMID 34539892, 2021). "Taken together, this study demonstrated that circITGA7 promoted glioma proliferation via regulating miR-34a-5p/VEGFA axis." (PMID 33962397, 2021). "CCAT2 enhances cell proliferation and endothelial angiogenesis in glioma by increasing vascular endothelial growth factor A (VEGFA) through miR-424 and activating the PI3K/Akt signaling pathway." (PMID 33980320, 2021). "Glioma cells regulate angiogenesis through the angiogenic cytokine VEGFA, which signals to vascular endothelial cells in the tumor microenvironment." (PMID 34539892, 2021). "The overexpression of CCAT2 in HUVECs results in the activation of VEGFA and TGFβ, thereby promoting angiogenesis of glioma cells." (PMID 33912560, 2021). "Great attention has been focused on vascular endothelial growth factor A (VEGF-A), which is released by glioma cells and promotes angiogenesis." (PMID 32542524, 2021).
glioma (continued). "Our study firstly established a seven-gene signature comprising METTL3, COL18A1, NASP, PHLPP2, TIMP1, U2AF2, and VEGFA with a good capability for predicting survival in glioma." (PMID 34589481, 2021). "Gliomas stimulate the formation of new blood vessels through processes driven primarily by vascular endothelial growth factor A (VEGFA), which is the most important factor for promoting angiogenesis in tumors, including glioma 7,8." (PMID 34539892, 2021). "Our findings have shown circITGA7 and VEGFA functioned as a promoter in glioma, while miR-34a-5p was regarded as an inhibitor of oncogene." (PMID 33962397, 2021). "Through analysis and dual-luciferase report assay, we found that circITGA7 acts as a sponge for miR-34a-5p targeting VEGFA in glioma." (PMID 33962397, 2021). "Among these genes, LBH promotes angiogenesis in glioma through VEGFA-mediated ERK signaling under hypoxic conditions." (PMID 34604236, 2021). "Since several VEGFA studies on gliomas exist, it is expected that it will work as an accurate and effective predictor for glioma prognosis." (PMID 34394352, 2021). "Mechanistic experiments further indicated that circSCAF11 accelerated glioma tumorigenesis through the miR-421/SP1/VEGFA axis, providing a potential target for circRNAs and glioma treatment." (PMID 33407501, 2021). "Taken together, these findings support a notion that downregulation of B7H3 is associated with reduced VEGFA in IDH-mutated gliomas, and B7H3 and VEGFA further decrease in IDH-mutated gliomas with highly accumulated 2-HG level." (PMID 34079802, 2021). "Activation of ERK/AKT signaling in glioma cells plays an important role in indirectly activating VEGFA, which plays a crucial role in tumor angiogenesis 23,24 through the regulation of various endothelial functions 25,26,27." (PMID 34539892, 2021). "Mechanistically, our data revealed that circITGA7 reduced the expression of miR-34a-5p, promoted translation of downstream gene VEGFA, which promoted the growth of glioma." (PMID 33962397, 2021). "In conclusion, our study revealed a regulatory loop for the circITGA7/miR-34a-5p/VEGFA axis to regulate glioma development." (PMID 33962397, 2021). "The protein level of B7H3 is positively correlated with VEGFA, and both proteins are reduced in IDH1-mutated glioma samples and further decreased in 2-HGhigh gliomas." (PMID 34079802, 2021). "Surprisingly, a further drop of B7H3 and VEGFA was observed in 2-HGhigh gliomas compared to that in 2-HGlow glioma sections." (PMID 34079802, 2021). "Numerous signaling pathways have been implicated in VEGFA-induced endothelial cell proliferation, typically AKT and ERK, which activate glioma cells and indirectly activate VEGFA through their action on HIF-1α 31,32." (PMID 34539892, 2021). "Taken together, in the present study, we established an IRRS prognostic model, composed of VEGFA, SOCS3, SPP1, and TGFB2 core DE IRGs, for risk stratification and survival prediction for glioma patients." (PMID 34497663, 2021). "RPL34-AS1 exerts oncogenic activity partially by affecting angiogenesis in glioma by regulating the VEGFA and ERK/Akt signaling pathways." (PMID 34539892, 2021). "B7H3 and VEGFA are decreased in IDH-mutated gliomas and further reduced in 2-HGhigh gliomas compared to 2-HGlow glioma sections by IHC staining." (PMID 34079802, 2021). "Relatively, autocrine of VEGFA also played a crucial role in the development of tumors, such as glioma, gastric cancer, and colorectal cancer." (PMID 34480024, 2021). "Our study showed that circITGA7 regulates the proliferation and metastasis of glioma cell lines (SW1783&U373) by regulating the miR-34a-5p/VEGFA pathway." (PMID 33962397, 2021). "It was also reported in glioma tissues that some antiangiogenic factors, for example, vascular endothelial growth factor A (VEGFA), can be changed into pro-angiogenic isoforms in carcinogenesis." (PMID 32346127, 2020).
glioma (continued). "For instance, Sp1 promoted progression of glioma, colon cancer and ovarian cancer and in these cases Sp1 all functions through elevating VEGFA." (PMID 33187481, 2020). "LncRNA TUG1 upregulates VEGFA expression by binding to miR-34a-5p and miR-299 in in hepatocellular carcinoma cells and glioma cells, respectively." (PMID 32993787, 2020). "RNA immunoprecipitation results from a microarray study showed that LINC01116 competed with VEGFA to bind with miR-31-5p in tumorigenesis of glioma." (PMID 32315285, 2020). "cARF1 was overexpressed in our glioma specimens, was positively correlated with poor patient survival, and also promoted proliferation, invasion, and angiogenesis of hBMECs via VEGFA signaling." (PMID 32894165, 2020). "In the present study, we first identified ISL2 as a novel oncogene in glioma, which was overexpressed and mainly involved in glioma angiogenesis via VEGFA-mediated ERK signaling, according to both bioinformatics analyses and molecular experiments." (PMID 32894165, 2020). "Under hypoxic conditions, LBH is directly regulated by HIF-1, and promotes glioma angiogenesis in human brain microvessel endothelial cells through the VEGFA-mediated ERK signaling pathway." (PMID 33198677, 2020). "PAX6 is also involved in inhibiting angiogenesis in gliomas, as it is found to downregulate expression of vascular endothelial growth factor A (VEGFA), the main angiogenic factor overexpressed in GBM." (PMID 29716531, 2018). "It has been shown that miR-384 targets PIWIL4 3′-UTR and suppresses glioma cell malignancy via regulating the expression of cyclin D1, VEGFA, SNAI2, MMP-9, Bcl-2, Bcl-xL and Caspase 3 genes." (PMID 30583549, 2018). "Elevated VEGFA expression is correlated with increased tumor microvessel density, high tumor grade, and poor prognosis in gliomas." (PMID 29137376, 2017). "(K) Immunoblot with antibodies against HIF1α, Glut1, and VEGFA from protein lysates derived from CRISPR-IUE glioma overexpressing Daam2 or control." (PMID 29053101, 2017). "We demonstrated using western blot analyses that a dose-dependent decrease of VEGFA-expression was observed in glioma cells that were exposed to VP." (PMID 28790340, 2017). "Although DEXA is operating anti-angiogenetic, both xCT and VEGFA expression are elevated under DEXA treatment in glucocorticoid-sensitive gliomas." (PMID 24714627, 2014). "Here, we found that glioma cells also up-regulate VEGFA following DEXA application in a concentration-dependent manner." (PMID 24714627, 2014). "A large body of research literature incriminates vascular endothelial growth factor A (VEGF-A) as the most potential mediator of tumor-induced angiogenesis in glioma." (PMID 22159356, 2012). "EFEMP1-mediated suppression of glioma-cell expression of VEGFA would result in the suppression of VEGFA stimulation of angiogenesis, which is in addition to EFEMP1's direct inhibition of endothelial cells sprouting." (PMID 21955618, 2011). "Current anti-angiogenic agents such as bevacizumab, a humanized VEGFA antibody, have met with limited success in glioma patients due to its promoting cell invasion." (PMID 21955618, 2011). "Integrated DNA and RNA analysis of low-grade and high-grade proneural gliomas identified increased expression and gene amplification of several genes including GLIS3, TGFB2, TNC, AURKA, and VEGFA in proneural GBMs, with corresponding loss of DLL3 and HEY2." (PMID 20838435, 2010). "For example, the gene VEGFA, which is known to be important in glioma and generates more than 750 pertinent citations on its own, is 6th in the meta-analysis list but does not fall among the top 30 genes on any of the individual studies' lists." (PMID 19732454, 2009). "After this citation reduction for VEGFA, the meta-analysis list still generates 154 glioma/cancer/astrocytoma-related citations." (PMID 19732454, 2009).